IGF2 (insulin like growth factor 2)
Diseases named in the same sentence as IGF2 in open-access papers (continued):
Sharing a sentence is not in itself a finding about the gene and the disease.
heart failure (4 papers, 2019 to 2023). Inability of the heart to pump blood at an adequate rate to meet tissue metabolic requirements. "In humans, data on postnatal functions of Igf2 are scarce; however, a recent case–control study reports an association of high serum Igf2 levels with lower mortality from heart failure, implying a role of Igf2 in cardioprotection." (PMID 37541969, 2023).
hemangiopericytoma (4 papers, 2018 to 2024). An antiquated term that refers to benign or malignant mesenchymal neoplasms characterized by the presence of neoplastic spindle-shaped to round cells arranged around thin-walled branching vascular spaces. "Surgical pathology demonstrated a hemangiopericytoma and strong positive for IGF-2." (PMID 36211262, 2022).
invasive breast carcinoma (4 papers, 2008 to 2018). A carcinoma that infiltrates the breast parenchyma. "Together, these findings provide evidence that macrophages and fibroblasts are the main sources of IGF-1 and IGF-2 both at the primary and the metastatic site in invasive breast cancer." (PMID 29367764, 2018). "In 17 of 70 cases of benign breast lesion patients, IGF-2 was positive but its expression rate was lower than in invasive breast cancer." (PMID 22662119, 2012). "In our study, Among the 63 cases of breast invasive ductal cancer patients, 26 cases were positive for IGF2, and the rate of IGF-2 gene expression in the invasive breast cancer was higher than in the tumor-adjacent tissue." (PMID 22662119, 2012). "The observed significant prognostic value of both TOP2A and IGF2 in our sample supports the reliability of the performed analyses and urges further evaluation of the prognostic value of securin in invasive breast cancer." (PMID 18594525, 2008).
lysosomal disorder (4 papers, 2011 to 2025). "We present the SWAP design, a novel, structurally cohesive IGF2-based tag for modular receptor targeting during gene therapy for lysosomal storage disorders (LSDs)." (PMID 41023195, 2025). "Since then, this approach has been explored in several lysosomal storage disorders by generating IGF2-tagged recombinant enzymes for ERT or by incorporating this peptide tag into the viral cassettes for gene therapy." (PMID 37463048, 2023). "This supports SWAP as an alternative to existing IGF2 tags offering modular targeting of receptors and a more favourable ligand–receptor interaction profile that has significant potential to advance gene therapy for lysosomal storage disorders." (PMID 41023195, 2025).
neuroendocrine tumors (4 papers, 2010 to 2025). "Similar to many neuroendocrine neoplasms, SFTs are immunologically cold and downregulate a set of immune response genes, perhaps with further support from IGF2 itself." (PMID 40875449, 2025). "Neuroendocrine tumors originate from neuron-like cells that are able to send and receive signals from the nervous system, but also function as endocrine organs by producing hormones such as IGF2, with a systemic effect across distal tissues and organs." (PMID 40875449, 2025).
stomach cancer (4 papers, 2005 to 2022). "INS, IGF1 and IGF2 CNV and relative overexpression were detected in 13% of gastric tumours." (PMID 34554347, 2022).
synovial sarcoma (4 papers, 2009 to 2025). "The observed variation involved single genes whose overexpression has been associated with synovial sarcoma, including BCL2 and IGF2 as well as clusters of genes implicated in cell trafficking and differentiation." (PMID 19936258, 2009). "The IGF2/IGF1R/Akt-MAPK axis drives synovial sarcoma cells growth and migration." (PMID 34440844, 2021). "From a functional standpoint, all synovial sarcomas express IGF2." (PMID 34440844, 2021). "Loss of imprinting (LOI) concurrent to hypomethylation at the H19/IGF2 intergenic region has been observed in a limited number of primary synovial sarcomas and SYT-SSX expression has been shown to induce IGF2 in immortalized MRC5 fibroblasts and HEK 293 cells." (PMID 19936258, 2009).
transitional cell carcinoma of the bladder (4 papers, 2012 to 2025). "The purpose of this study was to determine the relationship between methylation status of the insulin-like growth factor 2 (IGF-2) gene and methylenetetrahydrofolate reductase (MTHFR) C677T gene polymorphisms in bladder transitional cell carcinoma tissues in a Chinese population." (PMID 23554734, 2012). "MTHFR 677 CC and CT genotypes might be one of the reasons that cause abnormal hypomethylation of the IGF-2 gene, and the aberrant CpG island hypomethylation of the IGF-2 gene may contribute to the genesis and progression of bladder transitional cell carcinoma." (PMID 23554734, 2012).
3-M syndrome (3 papers, 2013 to 2017). 3M syndrome is a primordial growth disorder characterized by low birth weight, reduced birth length, severe postnatal growth restriction, a spectrum of minor anomalies (including facial dysmorphism) and normal intelligence. "SRS is clinically similar to 3-M syndrome and has been associated with epigenetic alterations of the IGF2/H19 locus resulting in the loss of IGF2 expression." (PMID 24711643, 2014). "3-M syndrome is associated with a gene expression profile of reduced IGF2 expression and increased H19 expression similar to that found in Silver–Russell syndrome." (PMID 24148222, 2013). "Our previously published transcriptomic data from 3-M syndrome patients with null mutations in either CUL7, OBSL1 or CCDC8 revealed that IGF2 expression is significantly reduced." (PMID 24711643, 2014). "In conclusion, this study demonstrates that there is reduced expression of IGF2 in 3-M syndrome linking the pathogenesis to that of SRS." (PMID 24148222, 2013). "The mechanisms through which IGF2 expression is reduced in 3-M syndrome remain unclear." (PMID 24148222, 2013).
acute myeloid leukemia (3 papers, 2014 to 2023). Acute myeloid leukemia (AML) is a group of neoplasms arising from precursor cells committed to the myeloid cell-line differentiation. "PLAGL2 was shown to upregulate IGF2 expression levels in hematopoietic progenitors of acute myeloid leukemia and IGF2 harbors eight PLAG1/PLAGL2 consensus binding sites." (PMID 36437415, 2023). "Upregulation of IGF2 in solid tumors is well documented in a variety of cancers, including colorectal, ovarian, esophageal cancers, and in acute myeloid leukemia, and TCGA analysis shows that IGF2 is also overexpressed in HNC versus normal tissue." (PMID 34067117, 2021).
alcohol (3 papers, 2014 to 2021). "Lower IP-10 (β coefficient = −125.0, P = 0.017) and alcohol dependence (β coefficient = 71.8, P = 0.023) were associated with higher plasma IGF2." (PMID 25890304, 2015). "Alcohol dependence was also associated with lower CSF IGF2 (β coefficient = −0.07, P = 0.029)." (PMID 25890304, 2015).
astrocytoma (3 papers, 2009 to 2025). "For example, MMP9 induced IGFBP2-IGF2 complex proteolysis resulted in the extracellular release of free IGF2 with positive and biologic effect on astrocytoma cellular growth and migration." (PMID 19489099, 2009). "MMP‐9 has been shown to induce IGF‐2/IGFBP2 complex proteolysis resulting in the extracellular release of free IGF‐1 with positive and biological effect on astrocytoma cellular growth and migration." (PMID 29321953, 2018).
autoimmune disease (3 papers, 2022 to 2025). A disorder resulting from loss of function or tissue destruction of an organ or multiple organs, arising from humoral or cellular immune responses of the individual to their own tissue constituents. "In autoimmune diseases, IGF-2 was found to preprogram maturing macrophages to acquire anti-inflammatory phenotype by elevating OXPHOS50." (PMID 40394007, 2025).
chondrosarcoma (3 papers, 2016 to 2021). A malignant cartilaginous matrix-producing mesenchymal neoplasm arising from the bone and soft tissue. "Even early reports have shown that IGF-1 and IGF-2 maintain, in an autocrine manner, the high PG synthesis in in vitro chondrosarcoma models." (PMID 34069554, 2021). "Heterogeneous expression of IGF1R, IR, IGF2R, IGF1, IGF2, IRS1 and IGFBP3 was seen, both at the mRNA and protein levels, in chondrosarcoma cell lines." (PMID 27418340, 2016). "Thus, treatment of human chondrosarcoma cells with IGFBP3 or IGF inhibitors enhanced their apoptosis rate, whereas mice expressing Gli2 presented fewer tumors upon IGF-2 downregulation." (PMID 34069554, 2021).
chronic kidney disease (3 papers, 2012 to 2023). Impairment of the renal function secondary to chronic kidney damage persisting for three or more months. "In the RTN3 KO mouse model, we also found that deletion of RTN3 can activate the IGF2–Janus kinase 2 (JAK2) pathway, which may further lead to chronic kidney disease and renal fibrosis." (PMID 36925557, 2023).
Cushing syndrome (3 papers, 2013 to 2025). Cushing's syndrome (CS) encompasses a group of hormonal disorders caused by prolonged and high exposure levels to glucocorticoids that can be of either endogenous (adrenal cortex production) or exogenous (iatrogenic) origin. ", found that the percentage of IGF2 stained area was significant higher in ACC when compared to ACA, including non-functioning ACA (ACAn) and ACA with Cushing’s Syndrome (ACAc)." (PMID 39890749, 2025).
developmental delay (3 papers, 2012 to 2025). "PLAG1, HMGA2, and IGF1R patients exhibited a lower frequency of body asymmetry and of relative macrocephaly at birth and postnatal life, while IGF2 patients displayed an increased frequency of feeding difficulties, heart defects, skeletal malformations, and developmental delay." (PMID 39412159, 2025). "He did not present with any developmental delay or intellectual disability, which has been reported in 80% of the patients with IGF2 variants." (PMID 36268036, 2022).
ependymoma (3 papers, 2019 to 2022). A WHO grade II, slow growing tumor of children and young adults, usually located intraventricularly. "SHH signaling might also have a role in mediating the tumorigenicity of ependymomas due to the upregulation of GLI1-2 and the overexpression of the insulin-like growth factor-2 (IGF-2) ligand, one of the targets of SHH." (PMID 36358663, 2022). "Interestingly, several RELAFUS target genes such as L1CAM and IGF2 were not necessarily common in 293T and mouse ependymoma cells in our analyses, indicating the fact that the transcriptional programs activated by RELAFUS are context-dependent." (PMID 33685520, 2021).
hepatitis B (3 papers, 2011 to 2022). "The importance of IGF-2 in HCC development is further demonstrated in its relationship with risk factors of HCC such as hepatitis B and C." (PMID 21729319, 2011).
hepatitis C (3 papers, 2010 to 2025). "This anabolic effect is consistent with the recent finding that IGF2 and IGFBP2 levels and bone formation are increased in patients with osteosclerosis linked to hepatitis C." (PMID 20573191, 2010).
hyperandrogenism (3 papers, 2015 to 2025). Excessive secretion of androgens from the adrenal glands or gonads. "In a recent study, it was shown that oocytes from women suffering from hyperandrogenism have an increased expression of IGF2." (PMID 30148131, 2018).
Hypokalemia (3 papers, 2024 to 2025). An abnormally decreased potassium concentration in the blood. "Serum hypokalemia is a feature of IGF-2–secreting tumors in up to 50% of cases." (PMID 40270996, 2025).
infantile hemangioma (3 papers, 2015 to 2020). "Indeed, differences in the expression of genomic biomarkers have been reported in infantile hemangioma; e.g., insulin-like growth factor 2 (IGF-2) was found as highly expressed in proliferative lesions compared to involuting lesions." (PMID 26772808, 2016).
injury (3 papers, 2017 to 2022). Damage inflicted on the body as the direct or indirect result of an external force, with or without disruption of structural continuity. "The insulin‐like growth factor 1 (IGF‐1) receptor is activated either by Igf1 or by Igf2 and is neuroprotective following brain injury." (PMID 28961383, 2017). "We aimed to examine the hypothesis that reducing the expression of IGF2 using intrathecal IGF2 small-interfering RNA (siRNA) would attenuate the development of neuropathic pain in rats after spared nerve injury (SNI)." (PMID 34855889, 2021).
Intellectual disability (3 papers, 2013 to 2025). "Since IGF2 has a role in learning and memory and PTHS patients have profound intellectual disability, TCF4 regulation of IGF2 expression may be a determinant of cognitive dysfunction." (PMID 24058414, 2013).
liposarcoma (3 papers, 2020 to 2023). A usually painless malignant tumor that arises from adipose tissue. "Unexpectedly, autopsy revealed that big IGF-2 had been produced only by the preexisting SFT, not the peri-renal tumor, and that the peri-renal tumor was a dedifferentiated liposarcoma." (PMID 32993631, 2020).
lung disease (3 papers, 2019 to 2025). "Using multicolor immunohistochemistry, we demonstrated that protein expression levels of IGFBP2 as well as its selective ligands IGF1 and IGF2 were significantly downregulated in AEC2 cells of the lung disease groups compared with healthy controls." (PMID 40121473, 2025). "Accordingly, IGF2 signaling is a potential target for blocking the NB-induced development of pulmonary diseases in both current and ex-smokers." (PMID 38902841, 2024). "Our findings clearly show that altered IGF2-IR signaling in AT2s links TS to the pathogenesis of these two pulmonary diseases." (PMID 38902841, 2024). "In this setting, clinically available strategies that allow careful control of IGF2 expression within the normal range in the AT2 SC pool may be critical for preventing the pathogenesis of the two TS-induced pulmonary diseases." (PMID 38902841, 2024).
lymphoma (3 papers, 2006 to 2024). A malignant (clonal) proliferation of B- lymphocytes or T- lymphocytes which involves the lymph nodes, bone marrow and/or extranodal sites. "Specifically, the FF-induced lymphoma, its transplant, and a spontaneous lymphoma showed Dβ1Jβ1 recombination (left), whereas the IGF2-induced lymphoma, its transplant, HGF-induced lymphoma, IGF2+HGF-induced lymphoma, and another spontaneous lymphoma showed Dβ2J2 rearrangement (right)." (PMID 34539876, 2021). "PCR analysis of clonal rearrangement of the TCRβ gene locus demonstrated that all four (FF, IGF2, HGF, HGF+IGF2) induced lymphomas, like the spontaneous lymphomas grown at old age, had a prominent monoclonal Dβ-Jβ rearrangements." (PMID 34539876, 2021). "The same weekly injection of IGF2, HGF, and their combination induced lymphomas in 4/11 (36%), 3/8 (38%), and 6/9 (67%) mice, respectively." (PMID 34539876, 2021). "In this study, we aim to further test the robustness of using IGF2 and HGF to replace FF in this lymphoma mouse model and to investigate the role of microenvironment and estrogen signaling in tumor development." (PMID 34539876, 2021).
Miscarriage (3 papers, 2020 to 2024). A pregnancy that ends at a stage in which the fetus is incapable of surviving on its own, defined as the spontaneous loss of a fetus before the 22th week of pregnancy. "The IGF2 ApaI polymorphism in partners of recurrent spontaneous abortion (RSA) women could affect the IGF2 level of expression in the placenta and embryo and represent a risk factor for RSA susceptibility." (PMID 35626807, 2022). "Autophagy suppression of trophoblasts increase the cytotoxicity of NK cells and damage the trophoblasts invasion possibly by targeting IGF-2 and PEG10, respectively, which ultimately leads to miscarriage." (PMID 32398034, 2020).
multiple myeloma (3 papers, 2014 to 2021). "In U266B1 (multiple myeloma) and βTC (neuroendocrine pancreatic cancer), the cost/benefit ratio of the growth factor that was knocked out (respectively, IL6 and IGF2) was high enough to enable the KO clone to spread in the WT population and induce the collapse of cooperation, at least at high FBS." (PMID 34359576, 2021).
neurofibroma (3 papers, 2018 to 2025). An intraneural or extraneural neoplasm arising from nerve tissues and neural sheaths. "Another hypothesis could be due to the secretion of insulin‐like growth factor 2 (IGF2) by neurofibromas." (PMID 37143466, 2023). "However, further studies are needed to verify if the FBG levels in patients with NF1 can be accounted for by IGF2 produced by neurofibromas." (PMID 29694637, 2018). "A second hypothesis to explain the lower levels of FBG in patients with NF1 is derivate of the production of insulin-like growth factor 2 (IGF2) by neurofibromas." (PMID 29694637, 2018).
oesophageal cancer (3 papers, 2017 to 2023). "Here, the authors show that IGF2 produced by oesophageal cancer cells increases secretion of VEGF from cancer-associated fibroblasts resulting in systemic mobilization of bone marrow-derived cells and increased metastases." (PMID 28186102, 2017). "IMP2 expression leads to elevated levels of IGF2, which may activate MAPK and Jak-STAT signaling pathways and is associated with poor prognosis in esophageal carcinoma." (PMID 34503162, 2021). "Here we show that IGF2 secreted by inhibitor of differentiation (Id1)-overexpressing oesophageal cancer cells instigates VEGFR1-positive bone marrow cells in the tumour macroenvironment to form pre-metastatic niches at distant sites by increasing VEGF secretion from cancer-associated fibroblasts." (PMID 28186102, 2017). "In addition to stimulating proliferation, migration and tube-formation of endothelial cells, the IGF2-activated fibroblasts also promoted tumour malignancy in a multitude of ways such as enhancing the invasion of oesophageal cancer cells and migration of bone marrow cells by secreting VEGF." (PMID 28186102, 2017). "Analysis of patient serum samples showed that concurrent elevation of IGF2 and VEGF levels may serve as a prognostic biomarker for oesophageal cancer." (PMID 28186102, 2017).
osteosclerosis (3 papers, 2010 to 2025). Abnormally high bone density. "Patients with excess of other forms of pro-IGF-2, which do not contain the preptin sequence, do not develop osteosclerosis." (PMID 24847313, 2014).
pancreatic ductal adenocarcinoma (3 papers, 2010 to 2020). An infiltrating adenocarcinoma that arises from the epithelial cells of the pancreas. "IGF-2 is one of the targets for miR-615-5p to modulate the proliferation of pancreatic ductal adenocarcinoma cells." (PMID 32399056, 2020). "Over-expression of insulin-like growth factor 2 mRNA binding protein 3 (IMP3) is correlated with poor prognosis in pancreatic ductal adenocarcinoma (PDAC)." (PMID 25886367, 2015). "IGF-2, in comparison to IGF2BP3, was expressed not only in pancreatic ductal adenocarcinoma, but also in benign pancreatic tissue." (PMID 20178612, 2010).
periodontitis (3 papers, 2021 to 2026). An acute or chronic inflammatory process that affects the tissues that surround and support the teeth. "Evidence from a single in vivo study suggests that IGF-2 administration may be associated with reduced inflammatory activity and enhanced alveolar bone regeneration under experimental periodontitis conditions." (PMID 41597400, 2026). "The neuropeptide genes ADM, IGF2, PDYN, and RETN were intersected between periodontitis and MDD, and FOSB was a crosstalk gene related to these neuropeptides on the transcriptomic level." (PMID 34721734, 2021). "The results of ROC analysis showed that IGF2 was highly predictive in MDD and periodontitis." (PMID 34721734, 2021).